CXCR2 (C-X-C motif chemokine receptor 2)
Diseases named in the same sentence as CXCR2 in open-access papers (continued):
Sharing a sentence is not in itself a finding about the gene and the disease.
thyroid tumor (3 papers, 2014 to 2025). A benign or malignant neoplasm affecting the thyroid gland. "Importantly, we also observed that CXCR2 expression coexists with senescence markers in thyroid tumour samples, in line with the view that senescence is linked with inflammation." (PMID 25268744, 2014). "In parallel to these observations in vitro, we observed a correlation between increased CXCR2 expression and OIS markers immunopositivity in human thyroid samples, suggesting that IL-8/ CXCR2 axis limits thyroid tumour progression." (PMID 25268744, 2014). "Importantly, we observed that CXCR2 expression coexists with OIS markers in thyroid tumour samples, suggesting that CXCR2 contributes to senescence, thus limiting thyroid tumour progression." (PMID 25268744, 2014).
urinary tract infection (3 papers, 2011 to 2024). "Besides, CXCR1/CXCR2-knockout mice showed a deficiency in neutrophil migration and bacterial clearance in a urinary tract infection model, and decline in CXCR1/CXCR2 expression may worsen outcome of infections due to impaired neutrophil recruitment." (PMID 22152684, 2011).
viral encephalitis (3 papers, 2019 to 2025). Encephalitis resulting from viral infection. "CXCR2-deficient mice had reduced the blood–brain barrier permeability in viral encephalitis but the permeability was not affected by closed head injury, indicating a disease-specific response." (PMID 34638514, 2021). "In a murine model of viral encephalitis, astrocyte- and neuron-derived CXCL1, through its receptor CXCR2, facilitates neutrophil transmigration and blood–brain barrier (BBB) permeability." (PMID 40243443, 2025). "The chemokine Gro-KC in rats (CXCL1; related to IL-8 in humans) attracts neutrophils, utilizes CXCR2 as its receptor, and was found in high levels in the brains of rats dying from RVF encephalitis." (PMID 31220182, 2019).
adenoma (2 papers, 2019 to 2024). A neoplasm arising from the epithelium. "Among them, CXCR2 was drastically upregulated in the IBD and adenoma stage, which is corroborated by the general upregulation of its ligands, CXCL1-3 and CXCL5-8." (PMID 39409185, 2024).
amebiasis (2 papers, 2017 to 2022). A parasitic infectious disorder caused by amoebas. "Blockade of CXCR2 increased susceptibility of control non-antibiotic treated mice to amebiasis." (PMID 28817707, 2017).
amebic colitis (2 papers, 2017 to 2020). "We extended these studies in the mouse model of amebic colitis, demonstrating that mechanisms of dysbiosis-mediated increased susceptibility were downregulation of neutrophil CXCR2 and attendant failure of neutrophil recruitment to the site of infection." (PMID 28817707, 2017). "In conclusion, we demonstrated that antibiotic-induced dysbiosis mediated susceptibility to amebic colitis through decreased neutrophil recruitment to the gut, at least partially due to decreased surface expression of neutrophil CXCR2." (PMID 28817707, 2017). "In conclusion, dysbiosis increased the severity of amebic colitis due to decreased neutrophil recruitment to the gut, which was due in part to decreased surface expression on neutrophils of CXCR2." (PMID 28817707, 2017). "Indeed, it was shown that microbiota promotes the recruitment of Cxcr2-positive neutrophils that can protect from amebic colitis." (PMID 32041848, 2020).
aneurysm (2 papers, 2022 to 2024). Bulging or ballooning in an area of an artery secondary to arterial wall weakening. "It was also analyzed whether the concentrations of the studied proteins NF-κB p65, GRO-α, and CXCR2 depend on the size and number of aneurysms in patients with UIA." (PMID 36494512, 2022). "The relationship of the proteins tested with the size and number of aneurysms may indicate that the NF-κB p65 pathway and the GRO-α/CXCR2 axis could be potentially involved in the pathomechanism of IA development in humans." (PMID 36494512, 2022).
Anxiety (2 papers, 2019 to 2022). Intense feelings of nervousness, tension, or panic often arise in response to interpersonal stresses. "To further examine the role of Cxcl1 in anxiety-like behavior, we treated HFD mice with reparixin, which inhibits the Cxcl1 receptors Cxcr1 and Cxcr2." (PMID 30612898, 2019). "As the Cxcr2 mutant strain did not have a documented anxiety phenotype, we assumed this strain had no anxiety-like behaviours for this analysis; repeating this analysis excluding this strain resulted in similarly strong grouping by anxiety phenotype." (PMID 35422470, 2022).
aortic aneurysm (2 papers, 2021 to 2025). A ruptured aneurysm located in the wall of the proximal portion of the descending aorta proceeding from the arch of the aorta. "C-X-C motif chemokine ligands (CXCLs) demonstrate high levels of intercellular communication signaling in aortic aneurysms, and blocking the binding of CXCL2 to receptor CXCR2 can significantly reduce the extent of aortic dilation." (PMID 40141310, 2025).
Ascites (2 papers, 2021 to 2023). Accumulation of fluid in the peritoneal cavity (between the layers of the peritoneum that lines the abdomen). "The percentage of CXCR2+ monocytes in the patient's ascites was lower than that in the peripheral blood." (PMID 37403022, 2023). "Consequently, we evaluated if adipocyte-specific CXCR2 cKO influenced the chemokine signatures in OC-induced ascites using proteomic arrays." (PMID 34638514, 2021).
bacterial pneumonia (2 papers, 2023 to 2025). Acute infection of the lung parenchyma caused by bacteria (e.g., Streptococcus pneumoniae, Haemophilus influenzae, Chlamydia pneumoniae, Mycoplasma pneumoniae, and Legionella pneumophila). "Using conditional endothelial and epithelial CXCR2 knockout mice, we demonstrate that selective CXCR2 deletion in either compartment impairs neutrophil recruitment into the lung during bacterial pneumonia and reduces bacterial clearance." (PMID 40413164, 2025). "The C-X-C motif chemokine receptor 2 (CXCR2) ligands, CXCL1 and CXCL2, are critical molecules for neutrophil chemoattraction and host defense against bacterial pneumonia." (PMID 37275853, 2023).
chondrosarcoma (2 papers, 2013 to 2015). A malignant cartilaginous matrix-producing mesenchymal neoplasm arising from the bone and soft tissue. "In addition to this direct link of MIF-CXCR2 signaling towards integrin activation, MIF has been shown to induce the migration of human chondrosarcoma cells by upregulating the transcription of the αvβ3 integrin through PI3K/AKT/NF-κB signaling in a CXCR2- and CXCR4-mediated way." (PMID 23720662, 2013). "Specific simultaneous inhibition of CXCR1 and CXCR2 using blocking antibodies in human primary chondrocytes, or by siRNA in the JJ012 human chondrosarcoma cell line, resulted in reduced ECM production in micromass cultures." (PMID 25135253, 2015).
Chronic colitis (2 papers, 2022). A chronic inflammatory disease of the large intestine (colon, cecum and rectum). "Our data also support the notion that IL-22-mediated induction of CXC-family chemokines is functionally important in the recruitment of CXCR2+ neutrophils to the colon in chronic colitis." (PMID 36192482, 2022). "Blockade, genetic deletion of IL-22, or blockade of CXCR2, the common ligand for the CXC family of neutrophil-active chemokines, significantly attenuated disease in the TRUC model of chronic colitis." (PMID 36192482, 2022).
chronic kidney disease (2 papers, 2022 to 2025). Impairment of the renal function secondary to chronic kidney damage persisting for three or more months. "The IL-8/CXCR2 axis induces mitochondrial dysfunction, which accelerates the senescence process and fibrosis in renal tubular cells, potentially underlying the pathogenesis of chronic kidney disease (CKD)." (PMID 40521043, 2025).
chronic nasopharyngitis (2 papers, 2018 to 2024). "But side effects of taking the CXCR2 inhibitors include nasopharyngitis, headaches, and decreased neutrophil count, leaving the patient susceptible to respiratory infections and other infections." (PMID 38596679, 2024). "In the present study, we found that CXCL5 and CXCR2 were upregulated in NPC tissues compared with those in non-tumour tissues from patients with chronic nasopharyngitis." (PMID 29665837, 2018).
clear cell carcinoma (2 papers, 2020 to 2026). "We previously verified that CXCR1/2 were expressed in different human OTC lines and showed that epithelial adenocarcinoma cell lines (OVCAR-3, IGROV-1, and SKOV-3 cells) as well as a clear cell carcinoma cell line (JHOC-5) expressed both CXCR1 and CXCR2." (PMID 31504643, 2020).
cognitive decline (2 papers, 2023). "In this study, we revealed that CXCL5-CXCR2 signaling mediated a novel astrocyte-microglia circuit in CSVD, as astrocyte-derived CXCL5 aggravated WMI and cognitive decline via inhibiting microglial phagocytosis of myelin debris after binding to microglial CXCR2." (PMID 37138312, 2023).
cystitis (2 papers, 2009 to 2022). Inflammation of the urinary bladder. "The role of CXCR2 in the bladder function and visceral hypersensitivity in CYP-induced cystitis and the antinociceptive effect of a selective antagonist of CXCR2, SB225002, have been recently reported in another CYP-induced IC rat model." (PMID 35571079, 2022).
demyelinating disease (2 papers, 2010 to 2014). A broad group of disorders that affect the myelin sheaths that cover the neurons. "How CXCR2 signaling participates in initiating neuroinflammatory demyelinating diseases has recently been examined." (PMID 20596532, 2010). "KC and CXCR2 have been shown to be involved in oligodendrocyte precursor proliferation and migration in other mouse models of demyelinating diseases such as the cuprizone model, Jimpy mice (defective proteolipid protein), and mice with Theiler’s virus-induced demyelinating disease." (PMID 23755134, 2014).
dermatitis (2 papers, 2019 to 2025). An inflammatory process affecting the skin. "In fact, deficiency or inhibition of IL-1β or CXCR2 has been reported to suppress the onset of dermatitis." (PMID 41296413, 2025). "In other Cxcr2-knockout mouse models, significant decrease of neutrophil infiltration into the local area including dermatitis and PDAC has been reported." (PMID 30659170, 2019).
E. coli infection (2 papers, 2023 to 2025). "WT neonates downregulated CXCR2 expression levels in the spleen upon E. coli infection." (PMID 40977737, 2025). "We found a significantly upregulated expression of CXCL3 in human brain microvascular endothelial cells and U251 cells after meningitic E. coli infection, and the CXCL3 receptor, C-X-C motif chemokine receptor 2 (CXCR2), was expressed in microglia." (PMID 37445610, 2023). "In conclusion, our results indicate that meningitic E. coli infection promotes CXCL3 expression, and CXCL3 binds to CXCR2 to promote neuroinflammation by regulating downstream signaling pathways and expression of pro-inflammatory factors in microglia." (PMID 37445610, 2023).
endometrial adenocarcinoma (2 papers, 2009 to 2019). "They further showed that CXCL1 and CXCR2 expression was elevated in the cancer tissue and that PGF2α‐FP receptors signalling promotes CXCL1 expression on endometrial adenocarcinoma cells and attracts CXCR2‐expressing neutrophils." (PMID 30381825, 2019). "Recently we showed elevated expression of the chemokine (C-X-C motif) receptor 2 (CXCR2) in endometrial adenocarcinomas localized to neutrophils and neoplastic epithelial and vascular cells." (PMID 19819266, 2009).
epilepsy (2 papers, 2020 to 2025). A brain disorder characterized by episodes of abnormally increased neuronal discharge resulting in transient episodes of sensory or motor neurological dysfunction, or psychic dysfunction. "The role of CXCL1, a murine ortholog of the human chemokine CXCL8 (IL-8), and its receptors CXCR1 and CXCR2 in epilepsy was discussed in a previous study using a murine model." (PMID 40243443, 2025).
experimental autoimmune encephalomyelitis (2 papers, 2017 to 2021). An autoimmune demyelinating disease of the central nervous system that is produced experimentally in animals by the injection of homogenized brain or spinal cord in Freund's adjuvant. "The antibody strongly inhibits IL-8-induced and CXCR2-mediated neutrophil chemotaxis in vitro and alleviates hCXCR2-dependent experimental autoimmune encephalomyelitis symptoms in mice." (PMID 33953162, 2021).
familial Mediterranean fever (2 papers, 2023). Familial Mediterranean fever (FMF) is an autoinflammatory disorder characterized by recurrent short episodes of fever and serositis resulting in pain in the abdomen, chest, joints and muscles. "The second CXCR2 antagonist, AZD4721 (also known as RIST4721), is evaluated in phase II studies for two types of chronic inflammatory skin diseases and for Familial Mediterranean fever (FMF)." (PMID 36725964, 2023).
fungal infection (2 papers, 2015 to 2023). "IL-33 enhances macrophage cytokines secretion and CXCR2 expression in fungal infections to drive neutrophil recruitment and bactericidal capacity." (PMID 37153553, 2023). "First, lung and airway CXCL1 levels increase more rapidly than CXCL2 levels at the onset respiratory fungal infection and thus CXCR2-dependent trafficking steps may reflect the relative abundance of cognate ligands." (PMID 25621893, 2015).
glaucoma (2 papers, 2022 to 2025). Increased pressure in the eyeball due to obstruction of the outflow of aqueous humor. "The specific activation of Cdc42 by the IL-8/CXCR2 pathway emphasizes its critical role in the pathophysiology of viral-induced glaucoma, offering potential avenues for therapeutic intervention." (PMID 40353220, 2025). "In conclusion, CXCR2 might be a potential therapeutic target for glaucoma from view of a sclera‐based therapy." (PMID 36349481, 2022). "Specifically, targeting the IL-8/CXCR2/Cdc42 axis could provide a new approach to modulate TM cell motility and contraction leading to reducing outflow resistance and preventing the progression of glaucoma." (PMID 40353220, 2025).
graft versus host disease (2 papers, 2024). An immune system disorder that occurs after allogeneic hematopoietic stem cell transplant and is a reaction of donor immune cells against host tissues. "In addition, the antibody blockade of CXCR2 signaling reduces the expression levels of tissue IL-23 in the liver and intestine at the initial stage of graft-versus-host disease (GVHD) and attenuates disease severity." (PMID 38312837, 2024).
helminth infection (2 papers, 2015 to 2022). "We have more recently established that tuft cell responses to N. brasiliensis are intact in CXCR2-deficient mice (S.L., F.V., Dyer, D., Graham, G., and R.M.M., in preparation), suggesting that one of the other receptor subunits is critical in helminth infection." (PMID 35288645, 2022). "Several studies have implicated CXCR2 in granulocyte recruitment during helminth infection." (PMID 25806513, 2015). "To assess a potential role for CXCR2 in intestinal repair during helminth infection in vivo, we treated mice by the orally active CXCR2 antagonist SB265610." (PMID 25806513, 2015). "Taken together these findings suggest that helminth-antibody-MΦ interactions can promote CXCR2 dependent wound closure during helminth infection across distinct host and parasite species." (PMID 25806513, 2015). "CXCR2 ligation was required for wound containment during murine helminth infection in vivo, and for efficient wound closure by human MF in vitro." (PMID 25806513, 2015). "Taken together, these findings implicate CXCR2 as an important immune-modulating pathway, which functions to promote wound contraction following helminth infection but does not contribute to granulocyte recruitment." (PMID 25806513, 2015).
hematoma (2 papers, 2018 to 2025). A hematoma is a collection of blood from a vascular structure into an extravascular space. "Collectively, these findings indicate that the CXCR2–JAKs–STATs–MMPs signaling may be activated by immune cells—particularly microglia—around the hematoma following ICH." (PMID 40994248, 2025).
Hepatitis (2 papers, 2022). Inflammation of the liver. "From the health to hepatitis, the MIF signaling network and related ligand-receptor interactions, including MIF-(CD74 + CXCR4), MIF-(CD74 + CXCR2), and MIF-(CD74 + CD44) showed a significant effect on macrophage–naïve CD4 + T cell interaction." (PMID 36221095, 2022).
HIV-1 infection (2 papers, 2014 to 2018). The type species of lentivirus and the etiologic agent of acquired immunodeficiency syndrome (AIDS). "Decreased expression of CXCR2 is associated with cellular activation and has been reported in septic shock, HIV-1 infection, autoantibody (ANCA)-associated vasculitis, after cardiopulmonary bypass, and others." (PMID 30540818, 2018). "Overall, our study shows that CXCL8 enhances HIV-1 infection in macrophages and microglia through receptors CXCR1 and CXCR2 by downstream activation of NF-κB." (PMID 24662979, 2014).
Hypercholesterolemia (2 papers, 2013 to 2023). An increased concentration of cholesterol in the blood. "Physiological concentrations of estradiol modulated basal and hypercholesterolemia-induced increases in chemokine receptor CXCR2." (PMID 37180115, 2023). "An alternative role of CXCR2 in atherogenesis was unveiled by our findings that its ligand CXCL1 mediates mobilization of classical monocytes under hypercholesterolemia." (PMID 23417922, 2013). "In addition, at physiological concentrations, estradiol mediates monocyte adhesion as well as basal and hypercholesterolemia-induced increases in CXCR2 and MCP-1 expression." (PMID 37180115, 2023). "Increased CXCL1 levels accompanied by higher expression of its receptor CXCR2 on classical monocytes and inhibition of monocytosis by CXCL1-neutralization indicated a preferential role for the CXCL1/CXCR2 axis in mobilizing classical monocytes during hypercholesterolemia." (PMID 23417922, 2013).
Hyperglycemia (2 papers, 2021 to 2025). An increased concentration of glucose in the blood. "Our data support the concept that hyperglycemia strongly increases the expression of CXCR2 and its ligand CXCL1/KC." (PMID 34571976, 2021). "The results revealed an increased MAPK13, TSP1, and CXCR2 with hyperglycemia." (PMID 41514867, 2025). "Our findings of increased CXCR2 in diabetic control and healed tissues, as well as in fibroblasts (in vitro studies), further support the notion that hyperglycemia increases expression of CXCR2 and increased IL-8 signaling may contribute to delayed wound healing." (PMID 41514867, 2025). "This study aims to investigate the effects of hyperglycemia on the expression of MAPK13, CXCR2, and TSP-1." (PMID 41514867, 2025). "Overall, the results of this study suggest that hyperglycemia modulates the expression of MAPK13, TSP1, and CXCR2." (PMID 41514867, 2025). "The results of this study indicate the effects of hyperglycemia on the gene and protein expression of MAPK13, TSP1, and CXCR2, the mediators with a critical role in wound healing." (PMID 41514867, 2025). "The results suggest that hyperglycemia increases the expression of TSP1 and CXCR2, and the effects on MAPK13 are context-dependent." (PMID 41514867, 2025). "Study limitations and future direction: This study highlights the role of hyperglycemia in modulating the gene and protein expression of MAPK13, TSP1, and CXCR2." (PMID 41514867, 2025). "In vitro studies showed that hyperglycemia increases the protein expression of MAPK13, TSP1, and CXCR2 at 24 h in rat fibroblasts compared to control cells, as evidenced by increased fluorescence." (PMID 41514867, 2025).